DCTN1 (dynactin subunit 1)
Diseases named in the same sentence as DCTN1 in open-access papers (continued):
Sharing a sentence is not in itself a finding about the gene and the disease.
lung adenocarcinoma (4 papers, 2022 to 2025). A carcinoma that arises from the lung and is characterized by the presence of malignant glandular epithelial cells. "The female lung adenocarcinoma patient (concurrent EGFR mutations and DCTN1–ALK fusion) with brain metastases developed resistance to chemotherapy or targeted therapy." (PMID 41246301, 2025). "The lung adenocarcinoma patient harboring dual DCTN1–ALK and ALK-CLIP4 rearrangements showed PR to crizotinib with a 12-month progression-free survival (PFS) and received alectinib as second-line treatment." (PMID 41246301, 2025). "Here, we report a 46-year-old female who was diagnosed with lung adenocarcinoma and identified carrying concurrent DCTN1-ALK and ALK-CLIP4 rearrangements by next generation sequencing (NGS) (638-gene panel)." (PMID 35212154, 2022).
proteinopathies (4 papers, 2020 to 2025). "Mutations in DCTN1 have been linked to various TDP-43 proteinopathies such as Perry syndrome, lower motor neuron disease, ALS and ALS/FTD." (PMID 40395983, 2025). "DCTN1 is causative of Perry disease, which has been classified into a type of TDP-43 proteinopathy distinct from ALS/FTD." (PMID 33924373, 2021). "Interestingly, all these DCTN1-linked NDs are characterised by TDP-43 pathology hinting towards a direct link between axonal transport and TDP-43 proteinopathies." (PMID 40395983, 2025). "Taken together, these results support a model in TDP-43 proteinopathy, including Perry disease: dysregulation of DCTN1-TDP-43 interactions disrupts dynein-dependent retrograde transport of TDP-43 and causes cytoplasmic mislocalization and aggregation of TDP-43, with concurrent aggregation of DCTN1." (PMID 33924373, 2021). "Dysregulation of multiple interactions among dynein/kinesins, DCTN1, and TDP-43 may perturb RNA transport and cause cytoplasmic mislocalization and aggregation of TDP-43, both of which could contribute to the pathogenesis of Perry disease or other TDP-43 proteinopathies." (PMID 33924373, 2021). "Two different groups of missense mutations within the DCTN1 CAP-Gly domain are known to cause Perry disease, accompanying TDP-43 proteinopathy, or HMN7B, with no detectable TDP-43 proteinopathy." (PMID 33924373, 2021). "We thus identified DCTN1 as a new player in TDP-43 cytoplasmic-nuclear transport, and showed that dysregulation of DCTN1-TDP-43 interactions triggers mislocalization and aggregation of TDP-43, thus providing insights into the pathological mechanisms of Perry disease and other TDP-43 proteinopathies." (PMID 33924373, 2021).
diabetes (3 papers, 2023 to 2024). "Increased Dctn1 mRNA expression has been observed in the islets of obese mice (New Zealand obese mice) and increased protein expression of Dctn1 is considered to be a novel biomarker for diabetes." (PMID 39000422, 2024).
gastric cancer (3 papers, 2015 to 2025). A primary or metastatic malignant neoplasm involving the stomach. "Given the rarity of both ALK mutation and the fusion type, here, we report a case of a gastric cancer patient with a driver mutation of DCTN1–ALK fusion." (PMID 41246301, 2025).
progressive supranuclear palsy (3 papers, 2022 to 2025). A rare late-onset neurodegenerative disease characterized by supranuclear gaze palsy, postural instability, progressive rigidity, and mild dementia. "However, patients with pathogenic DCTN1 mutations may exhibit more diverse phenotypes, such as progressive supranuclear palsy- and/or FTD-like syndromes as well as distal hereditary motor and sensor neuropathies." (PMID 37330543, 2023).
cognitive decline (2 papers, 2019 to 2021). "DCTN1 mutations may present with features of PSP and CBD including atypical parkinsonism, cognitive decline, saccadic abnormalities, vertical gaze palsy, falls, myoclonus, and dystonia." (PMID 34396589, 2021).
depression (2 papers, 2020). "Previously discovered disease-causing variants in DCTN1 (e.g., in PS, ALS) are inherited in an autosomal-dominant fashion, and disease-causing variants in PS (resulting in atypical PD) are already known to also result in severe depression." (PMID 32325768, 2020).
Histiocytosis (2 papers, 2023 to 2025). An excessive number of histiocytes (tissue macrophages). "The present study reports a pediatric case of ALK-positive histiocytosis with DCTN1::ALK gene rearrangement." (PMID 40361876, 2025). "In summary, we present a rare case of ALK-positive histiocytosis with unusual DCTN1 fusion." (PMID 40361876, 2025). "The VRK2-ALK and DCTN1-ALK fusion thus may lead to activation of ALK gene driving the tumorigenesis in the ALK-positive histiocytosis." (PMID 36915094, 2023). "Herein, we present the case of a 6-month-old infant with mono-systemic, cutaneous ALK-positive histiocytosis harboring DCTN1::ALK fusion." (PMID 40361876, 2025).
Huntington disease (2 papers, 2017 to 2020). Huntington disease (HD) is a rare neurodegenerative disorder of the central nervous system characterized by unwanted choreatic movements, behavioral and psychiatric disturbances and dementia. "Additionally, the extensive alteration of apoptosis in severe WS is emphasized by the increased abundance of dynactin subunit 1 (DCTN1) coupled with decreased axonemal heavy chain 3 of dynein (DNAH3), highlighted in Huntington disease pathway." (PMID 32612536, 2020). "We also found many differentially expressed genes related to the Huntington disease (HD) pathway in both areas of the MPS II mouse model; among these, Bbc3, Bdnf, Crebbp, Dctn1, Dlg4, Gpx1, Grin1, Grin2b, Itpr1, and Pparg are up-regulated, while Dnaic2, Dnali1, Hap1, and Vdac2 are down-regulated." (PMID 28513549, 2017).
Hyperglycemia (2 papers, 2024 to 2025). An increased concentration of glucose in the blood. "Two amplifiers further erode the diaphragm: hyperglycemia accelerates dynein-dependent nephrin degradation (DynII1/DCTN1), and anti-nephrin autoantibodies add an immune hit with ATP-depletion-related cytoskeletal injury." (PMID 41009556, 2025).
sporadic amyotrophic lateral sclerosis (2 papers, 2017 to 2019). Sporadic amyotrophic lateral sclerosis is a amyotrophic lateral sclerosis in which there is no known cause, such as no family history. "Novel mutations of DCTN1 in Chinese patients with sporadic amyotrophic lateral sclerosis." (PMID 28792508, 2017).
atrial fibrillation (1 paper, 2021). A disorder characterized by an electrocardiographic finding of a supraventricular arrhythmia characterized by the replacement of consistent P waves by rapid oscillations or fibrillatory waves that vary in size, shape and timing and are accompanied by an irregular ventricular response. "Novel variants in DCTN1, MYH14, and RBM20 were identified in Family 1 with cardiac and limb-girdle muscle involvement and in TRIM63, ACTC1, and TTN in the proband of family 2 with a distal lower limb phenotype and atrial fibrillation." (PMID 33170376, 2021).
bipolar disorder (1 paper, 2020). A disorder of the brain that causes unusual shifts in mood, energy, activity levels and the ability to carry out day-to-day tasks. "A novel cosegregating splice site variant in the Dynactin-1 (DCTN1) gene was discovered by Next Generation Sequencing (NGS) in a family with a history of bipolar disorder (BD) and major depressive diagnosis (MDD)." (PMID 32325768, 2020).
cataract (1 paper, 2025). Partial or complete opacity of the crystalline lens of one or both eyes that decreases visual acuity and eventually results in blindness. "Across all cataract groups, actin and microtubule cytoskeletal proteins (ACTN4, DCTN1, TUBA1C, TBCB, TUBB4A) were significantly downregulated compared to controls, with the most marked suppression in ARC." (PMID 41283652, 2025). "Specifically, proteins including ACTN4, DCTN1, MYO18A, TUBA1C, TBCB, and TUBB4A, were downregulated in all cataract groups compared to controls." (PMID 41283652, 2025).
Cognitive impairment (1 paper, 2020). Abnormal cognition is characterized by deficits in thinking, reasoning, or remembering. "The DCTN1 p.Val496Leu variant, which was located in the dynein binding domain and predicted as pathogenic, was identified in a fALS patient presenting with a classic phenotype and no cognitive impairment." (PMID 32397312, 2020).
colon adenocarcinoma (1 paper, 2019). "DCTN1, DCTN2, and DCTN4 could serve as biomarkers to predict the prognosis and diagnosis of colon adenocarcinoma (COAD)." (PMID 31847905, 2019).
colorectal cancer (1 paper, 2024). A primary or metastatic malignant neoplasm that affects the colon or rectum. "In addition, there is also a study showing that the expression level of DCTN1 in colorectal cancer tissues is higher than that in adjacent tissues, which may be an oncogene in colorectal cancer." (PMID 38466053, 2024).
cutaneous melanoma (1 paper, 2022). A primary melanoma arising from atypical melanocytes in the skin. "Low expression of DCTN1 in primary tumors has been reported to be associated with favorable prognosis in patients with cutaneous melanoma and low-grade glioma." (PMID 36291758, 2022).
juvenile myelomonocytic leukemia (1 paper, 2022). A myelodysplastic/myeloproliferative neoplasm of childhood that is characterized by proliferation principally of the granulocytic and monocytic lineages. "In a genomic study of patients with juvenile myelomonocytic leukemia (JMML), 16 patients had no RAS variants, and in three of these that were 56 months of age or older, the researchers identified ALK/ROS1 tyrosine kinase fusions (DCTN1-ALK, RANBP2-ALK, and TBL1XR1-ROS1)." (PMID 36295546, 2022).
limb-girdle muscular dystrophy (1 paper, 2021). Limb-girdle muscular dystrophy (LGMD) is a heterogeneous group of muscular dystrophies characterized by proximal weakness affecting the pelvic and shoulder girdles. "The genetic structure variability of the DCTN1 gene was involved in the development of the limb-girdle muscular dystrophy and neuron differentiation." (PMID 34168979, 2021).
lung carcinoma (1 paper, 2022). "DCTN1 has been identified as an anaplastic lymphoma kinase (ALK) fusion partner in lung cancer." (PMID 36291758, 2022).
mastitis (1 paper, 2025). Inflammation of breast tissue during lactation or postpartum due to an obstructed duct or infection. "The DCTN1, MYOF, and DPP9 genes encode key regulators of intracellular transport, membrane repair, and protein degradation, respectively, and their expression changes driven by miR-223 suggest a comprehensive modulation of immune response and cellular resilience during mastitis." (PMID 40033327, 2025). "By regulating critical genes such as PTPRF, DCTN1, and DPP9, miR-223 emerges as a key molecular modulator that balances cellular processes, contributing to mastitis resistance and production traits like milk yield and fat content." (PMID 40033327, 2025). "The identification of DEGs and potential target genes, particularly PTPRF, DCTN1, PLEC, MYOF, and DPP9, underscores the critical role of miR-223 in modulating mastitis-related traits in dairy cattle." (PMID 40033327, 2025).
metastatic melanoma (1 paper, 2020). A melanoma that has spread from its primary site to another anatomic site. "In metastatic melanoma, DCTN1 was found to be associated with the presence of T cell-inflammation while ITGAX (alias CD11c) is more frequently mutated in non-T cell-inflamed tumors." (PMID 33106165, 2020).
motor neuron degeneration (1 paper, 2014). "Mutation in Dctn1 gene has been associated to motor neuron degeneration in ALS and downregulation of the gene was described in residual motor neurons of postmortem material of ALS patients." (PMID 24904291, 2014).
osteosarcoma (1 paper, 2021). A usually aggressive malignant bone-forming mesenchymal neoplasm, predominantly affecting adolescents and young adults. "The mGFP control or DCTN1-mGFP (wild-type or mutants) and mCherry-TDP-43 (wild-type) are transiently transfected into human osteosarcoma U2OS cells, and the cells were cultured under nonstressed conditions." (PMID 33924373, 2021).
pancreatic tumors (1 paper, 2025). "To date, the DCTN1–ALK fusion gene has been reported in three cases of NSCLC, one case of IMT, six cases of Spitz tumors, one case of epithelioid fibrous histiocytoma, and one case of pancreatic tumors." (PMID 41246301, 2025).
prostate carcinoma (1 paper, 2024). A carcinoma that arises from epithelial cells of the prostate gland. "Dysregulated expression of DCTN1 has been reported in several cancers, and here we revealed altered DCTN1 expression in prostate cancer tumours, suggesting its potential involvement in the pathogenic process." (PMID 39217195, 2024). "ALK fusions with DCTN1 or other lysosome trafficking proteins may impair lysosomal traffic and maturation, promoting increased ALK signalling through perturbed lysosomal degradation, facilitating prostate cancer development." (PMID 39217195, 2024).
Salmonella Infections (1 paper, 2023). Infections with bacteria of the genus SALMONELLA. "The proteins with the greatest significance or fold change for “Salmonella Infection” are Dynactin Subunit 1 (DCTN1) and Cytochrome C (CYC2), respectively." (PMID 37566063, 2023).
schizophrenia (1 paper, 2020). A major psychotic disorder characterized by abnormalities in the perception or expression of reality. "DCTN1 is located on 2p13.1, which is within a region previously found to show significant linkage in autosomal dominant models for BD (2p13–16) and schizophrenia (2p13–14)." (PMID 32325768, 2020).
tauopathy (1 paper, 2023). Neurodegenerative disorders involving deposition of abnormal tau protein isoforms (tau proteins) in neurons and glial cells in the brain. "However, given the rare reports, the molecular interplay between DCTN1 and Tauopathy is still unknown and awaits confirmation." (PMID 36982356, 2023).
uterine neoplasm (1 paper, 2015). "This case harbors a DCTN1-ALK fusion which has been previously reported but is described here in a myxoid uterine neoplasm for the first time." (PMID 26062823, 2015).
neurodegenerative disease (10 papers, 2013 to 2025). A disorder of the central nervous system characterized by gradual and progressive loss of neural tissue and neurologic function. "Although consisting of 23 subunits, most dynactin mutations associated to neurodegenerative diseases are observed in the DCTN1 gene encoding for the dynactin subunit p150glued." (PMID 40589526, 2025). "Missense mutations in the dynactin gene (DCTN1) encoding dynactin subunit-1 are linked to several neurodegenerative diseases." (PMID 41463293, 2025). "For example, DCTN1 encodes the dynactin-1 protein, and deficits in dynactin are connected to several neurodegenerative diseases; however, there is limited research linking this gene to AD." (PMID 38635981, 2024). "Thus, mitochondria are a possible therapeutic target in DCTN1-linked human neurodegenerative diseases." (PMID 41463293, 2025). "DCTN1 mutations have also been implicated in some neurodegenerative diseases." (PMID 36291758, 2022). "With regard to DCTN1, closely apposed mutations in its CAP-Gly domain cause two distinct neurodegenerative diseases: distal hereditary motor neuropathy 7B (HMN7B) and Perry disease (Perry syndrome)." (PMID 33924373, 2021). "Our hypothesis that dysregulation of DCTN1–TDP-43 interactions and/or the imbalance in DCTN1 expression perturb TDP-43 transport from axonal tips to the nucleus, and cause TDP-43 aggregation in the cytoplasm and axoplasm may also be applicable to ALS or ALS-related neurodegenerative diseases." (PMID 33924373, 2021). "DCTN1 is reduced in mice with spinal and bulbar muscular atrophy (SBMA), a hereditary neurodegenerative disease and over-expression of DCTN1 mitigated neuronal toxicity of the pathogenic androgen receptor in a cell culture model of SBMA30." (PMID 29915338, 2018).
cancer (8 papers, 2015 to 2025). A tumor composed of atypical neoplastic, often pleomorphic cells that invade other tissues. "The appearance of the DCTN1–ALK fusion gene in cancer is a rare genetic rearrangement event primarily associated with the occurrence and progression of tumors." (PMID 41246301, 2025). "We also analysed the effects of PAFAH1B1 and DCTN1 on OS in various cancers, and found that the high expression of these two genes is associated with poor prognosis of various cancers." (PMID 38466053, 2024). "Both PAFAH1B1 and DCTN1 are shown to promote cancer in specific cancers, while NDE1 has mutual binding properties with PAFAH1B1 and DCTN1, respectively." (PMID 38466053, 2024). "DCTN1, GALC and GALNS also are not known cancer genes in the COSMIC database." (PMID 38310436, 2023).
tumor (8 papers, 2015 to 2025). "The whole blood circulating tumor DNA (ctDNA) gene test revealed the disappearance of the original DCTN1–ALK fusion and the concomitant emergence of a de novo KRAS amplification mutation." (PMID 41246301, 2025). "It is supposed that the KRAS amplification mutation replaced DCTN1–ALK fusion to emerge as the driver gene, precipitating rapid and widespread tumor progression." (PMID 41246301, 2025). "Four somatic variations (RP1L1, PRB1, HS6ST3 and DCTN1) were simultaneously occurred in both primary tumor and PM cancer." (PMID 26330360, 2015). "In addition, genes including BRAF, DCTN1 and RAD51B were among the 20 tumour-related genes that were found to be mutated only in the PTCa and PTCb patients." (PMID 36686473, 2022). "When DCTN1 undergoes a gene fusion with ALK, it may lead to the abnormal activation of the ALK kinase, thereby promoting the proliferation and survival of tumor cells." (PMID 41246301, 2025). "When DCTN1 undergoes a gene fusion with ALK, DCTN1 is suspected to promote the dimerization of ALK and lead to the abnormal activation of the ALK kinase by transphosphorylation, thereby promoting the proliferation and survival of tumor cells." (PMID 41246301, 2025). "Although the index detection of DCTN1–ALK was tissue-based, subsequent resistance profiling relied on cfDNA; therefore, we cannot determine whether the KRAS-amplified sub-clone originated from the primary tumor, bone metastases, or both." (PMID 41246301, 2025). "It seems that DCTN1, as a fusion partner of ALK, does not predispose one to a specific clinical manifestation, disease course, or histological appearance; however, due to the rarity of this tumor entity, it is crucial to perform a larger study to elucidate this issue." (PMID 40361876, 2025).
infection (3 papers, 2021 to 2025). The state of being infected such as from the introduction of a foreign agent such as serum, vaccine, antigenic substance or organism. "Thus, external application of VPS51+DCTN1+SAC1‐dsRNA inhibits infection of Botrytis cinerea, S. sclerotiorum and A. niger." (PMID 33774895, 2021). "HSV-1 maintains infectivity across varying DCTN1 expression levels without perturbing mitochondrial function, whereas DCTN1 competitively disrupts HIV-1’s early infection cycle by sequestering cytoplasmic linker protein 170 (CLIP-170)." (PMID 41142773, 2025).
movement disorder (2 papers, 2015 to 2021). Neurological conditions resulting in abnormal voluntary or involuntary movement, which may impact the speed, fluency, quality and ease of movement. "This Movement Disorder Society Genetic mutation database Systematic Review focuses on monogenic atypical parkinsonism with mutations in the ATP13A2, DCTN1, DNAJC6, FBXO7, SYNJ1, and VPS13C genes." (PMID 34396589, 2021).
brain disorder (1 paper, 2021). A disease affecting the brain or part of the brain. "The network revealed that the majority of the disorders are linked with DYNC1H1 (k = 91), LMNA (k = 86), FMR1 (k = 74), DCTN1 (k = 57), and ALDH18A1 (k = 54) genes and showed interactions with multiple brain disorders." (PMID 34832615, 2021). "Interestingly, out of five key SG genes that showed a high number of associations with brain disorders, three genes, namely LMNA (k = 14), DCTN1 (k = 8), and ALDH18A1 (k = 4), also play important roles in disorders having a major impact on lungs and respiratory ability of the patients." (PMID 34832615, 2021).